CD83 (CD83 molecule)
Diseases named in the same sentence as CD83 in open-access papers (continued):
Sharing a sentence is not in itself a finding about the gene and the disease.
meningioma (1 paper, 2024). A generally slow growing tumor attached to the dura mater. "This suggests that both TIM3+ and TIM3+CD83+ macrophages in meningioma may have an immunosuppressive role." (PMID 39682129, 2024). "Further investigations of the immune cells and macrophages in two meningiomas revealed expression of the immune checkpoint inhibitor TIM-3 and CD83, an activation marker of M1 macrophages." (PMID 39682129, 2024).
mucinous carcinoma (1 paper, 2023). "We noticed the most numerous mature DCs (expressing CD83 or DC-LAMP) in the mucinous carcinoma samples." (PMID 36768258, 2023).
mycosis (1 paper, 2021). "Fold changes in fluorescence (fold changes in percentage of positive DCs in the case of CD83) were compared to investigate the donor dependence effect, and we also compared the two groups of commercial and mycosis causing isolates." (PMID 34575784, 2021).
oesophageal adenocarcinoma (1 paper, 2020). "TCM from oesophageal adenocarcinoma significantly enhanced CD54 (p < 0.001), CD80 (p < 0.001), HLA-DR (p = 0.001), CD86 (p < 0.001) and CD83 (p < 0.001) compared to LPS-induction in background media alone, cM199 (+)." (PMID 32552799, 2020).
osteoarthritis (1 paper, 2020). A noninflammatory degenerative joint disease occurring chiefly in older persons, characterized by degeneration of the articular cartilage, hypertrophy of bone at the margins and changes in the synovial membrane. "LAMP3 was one of the differentially expressed genes between RA and osteoarthritis patients, and CD83 was expressed in more than 20% of pDCs in the RA synovium." (PMID 32164778, 2020).
ovarian serous adenocarcinoma (1 paper, 2020). An adenocarcinoma that arises from the ovary and is characterized by the presence of malignant epithelial cells that, in well differentiated tumors, resemble the epithelium of the fallopian tube or, in poorly differentiated tumors, show anaplastic features and marked nuclear atypia. "Second, CD83 expression was significantly upregulated in ovarian serous adenocarcinoma cell lines (e.g., SKOV3, OVCAR3, and Caov3) as compared with ovarian surface epithelial cell HOSEpiC." (PMID 32823589, 2020). "Immunostaining analysis further indicated the ectopically activated CD83 expression in human ovarian serous adenocarcinoma, as compared with that in para-cancer tissues." (PMID 32823589, 2020).
pancreatic cancer (1 paper, 2023). "To investigate the effect of CD83 overexpression on antitumor efficacy of CAR-T cells in vivo, we infused mesothelin-targeting CAR-T cells with or without ectopic expression of CD83 into NSG mice that were subcutaneously inoculated with the mesothelin-expressing pancreatic cancer cell line AsPC-1." (PMID 36906640, 2023).
papilloma (1 paper, 2020). A benign epithelial neoplasm that projects above the surrounding epithelial surface and consists of villous or arborescent outgrowths of fibrovascular stroma. "To determine whether PGE2 also affected iLC maturation, identified by CD83 expression, we exposed monocyte-derived iLCs from patients and controls to PGE2, IL-36γ (a proinflammatory cytokine constitutively expressed by papilloma cells), a combination of these mediators, or LPS as a positive control." (PMID 32210959, 2020).
periapical granuloma (1 paper, 2018). Chronic nonsuppurative inflammation of periapical tissue resulting from irritation following pulp disease or endodontic treatment. "The protocol for immunohistochemical procedures of TLR2, CD38, CD68 and CD83 have been standardized and the expression of each cell marker (TLR2, CD38, CD68 and CD83) within refractory periapical granuloma was identified." (PMID 30631444, 2018). "Refractory periapical granuloma consistently expressed TLR2 through lymphocytes and plasma cells (CD38+), macrophages and monocytes (CD68+) and mature dendritic cells (CD83+)." (PMID 30631444, 2018). "The co-expression of CD83 and TLR2 were identified in six periapical granuloma samples." (PMID 30631444, 2018).
periodontitis (1 paper, 2022). An acute or chronic inflammatory process that affects the tissues that surround and support the teeth. "The percentages of CD83+ and CD86+ cells (DC markers) were significantly higher in response to periodontitis saliva than healthy saliva." (PMID 36207325, 2022).
Pleural effusion (1 paper, 2021). The presence of an excessive amount of fluid in the pleural cavity. "An analogous finding showed that high co-expression of BTLA and B7-H4 on myeloid dendritic cells (mDCs) in peripheral blood and pleural effusions of pleural TB patients promoted a high level of CD83 and HLA-DR, which had a negative regulatory effect on mDCs and anti-TB immunity." (PMID 34163466, 2021).
pneumonia (1 paper, 2024). An acute, acute and chronic, or chronic inflammation focally or diffusely affecting the lung parenchyma, caused by an infection in one or both of the lungs (by bacteria, viruses, fungi, or mycoplasma.). "We did not observe associations between autopsy-confirmed pneumonia and the presence of CD83(+) microglia among AD subjects (p-value: 0.37, Odds ratio: 0.57, Fisher’s Exact Test)." (PMID 38987616, 2024).
polymyalgia rheumatica (1 paper, 2013). A syndrome characterized by pain, stiffness, and tenderness of the proximal muscle groups including the shoulder, pelvic girdle and the neck. "In a hu-SCID mouse model of GCA, activated CD83+ DCs in the artery of a polymyalgia rheumatica (PMR) patient attracted, retained and activated autoreactive T cells." (PMID 23837028, 2013).
preeclampsia (1 paper, 2019). Preeclampsia is a hypertensive disorder of pregnancy that is characterized by new-onset hypertension with proteinuria presenting after 20 weeks of gestation, and depending on mild or severe forms may initially present with severe headache, visual disturbances, and hyperreflexia. "Recently depletion or malfunction of T cell populations has been associated with recurrent spontaneous abortion and incidence of preeclampsia and higher numbers of CD209+ and CD83+ DC have been reported in the preeclamptic placental bed." (PMID 30949130, 2019).
prostate carcinoma (1 paper, 2011). A carcinoma that arises from epithelial cells of the prostate gland. "The majority of the studies provided information for the following surrogate markers: CD14 (prostate cancer 8/17 studies, RCC 7/12 studies), HLA-DR (prostate cancer 11/17, RCC 7/12), CD86 (prostate cancer 11/17, RCC 8/12), and CD83 (prostate cancer 9/17, RCC 9/12)." (PMID 21533099, 2011).
prostate tumors (1 paper, 2023). "Immunohistochemical analyses were performed to identify CD209+ (immature DC), CD83+ (mature DC), CD68+ (total MΦ) and CD163+ (M2-type MΦ) cells in the 99 prostate tumors." (PMID 37435060, 2023).
psoriasis (1 paper, 2019). An autoimmune condition characterized by red, well-delineated plaques with silvery scales that are usually on the extensor surfaces and scalp. "CD83 is a marker for mature/activated dendritic cells, which are a major source of TNF in psoriasis lesions and provide signals for direct intralesional T cell activation." (PMID 30953507, 2019).
rectal adenocarcinoma (1 paper, 2020). "Moreover, the TCM from rectal adenocarcinoma significantly enhanced CD80 (p = 0.028), CD86 (p = 0.016) and CD83 (p = 0.002) compared to LPS-induction in background media alone, cRPMI (+)." (PMID 32552799, 2020).
retinoblastoma (1 paper, 2025). A malignant tumor that originates in the nuclear layer of the retina. "Moreover, in the high-ICI subgroup, CD83, HLA-DOA, IRF4, DOK3, and CXCR1 genes were also hypermethylated and thus associated with the presence of retinoblastoma." (PMID 41150792, 2025).
small cell carcinoma (1 paper, 2010). A neuroendocrine carcinoma composed of small malignant cells which are often said to resemble "oat cells" under the microscope. "In the current study, 20 out of the 24 subjects (5 of the 8 controls and 17 of the 18 COPD samples) used in the immunohistochemical determination of CD83 had a diagnosis of either non-small cell or small cell carcinoma." (PMID 20420706, 2010).
synovial sarcoma (1 paper, 2021). "Taken together, sunitinib treatment of both bone and synovial sarcoma cells induced a significant upregulation of CD80, CD86, CD83 and CCR7 which are essential for full DC maturation." (PMID 33717062, 2021).
synovitis (1 paper, 2025). Inflammation of a synovial membrane. "APRIL was exposed to be particularly expressed in CD83+ dendritic cells, with the maximum expression in GC synovitis, while BAFF was similarly expressed across different types of synovitis and localized to CD68+ macrophages." (PMID 40821822, 2025).
thyroid carcinomas (1 paper, 2014). "We investigated 65 patients with different types of thyroid carcinomas: papillary (PTC), oncocytic (OTC), follicular (FTC) and anaplastic (ATC), immunohistochemically with antibodies against VEGF, CD1a, CD83, S100 and CD31." (PMID 26019537, 2014).
transplant related diseases (1 paper, 2022). "The biology of anti-CD83 antibodies has potential in the treatment of autoimmune, inflammatory or transplant related diseases." (PMID 35222372, 2022).
tularemia (1 paper, 2012). Tularemia is an infection caused by the bacterium Francisella tularensis. "In the early phase of tularemia, numerous neutrophils, monocytoid B cells (MBLs), histiocytic cells, T cells, S-100+, Langerin+, CD83+, CD163+ dendritic cells are found in lesions." (PMID 22588497, 2012).
uterine cancer (1 paper, 2024). Primary or metastatic malignant neoplasm involving the uterine corpus and/or the cervix. "Our study observed a higher CD83 concentration in patients with uterine cancer and endometrial cellular atypia." (PMID 39529763, 2024).
uveal melanoma (1 paper, 2016). A melanoma derived from melanocytes of the uveal tract. "Uveal melanoma cell co-cultured DCs exhibited decreased expression of CD1a and CD83 and impaired T cell activation." (PMID 27556503, 2016).
vasculitis (1 paper, 2014). "In contrast, we saw few CD83+ or CD206+ DCs in the lung in vivo at remission after treatment with corticosteroids, immunosuppressants, and IVIG, but this therapy did not affect the number of eosinophils, which is already high in patients with EGPA before the onset of vasculitis." (PMID 25174446, 2014).
tumor (150 papers, 2003 to 2026). "Based on the reduced expression of APC activation markers such as MHCII, CD11c, and CD83 on CD11b+ cells, we analyzed tumors for changes in the number of tumor-associated CD8 T cells and observed a decrease in TILs in CHRNA7KO mice compared with WT mice." (PMID 40653990, 2025). "Higher CD209+/CD83+ cell density ratio at the tumor margin was associated with higher risk of ADT and lethal PCa while higher density of CD163+ cells in the normal-like adjacent epithelium was associated with a higher risk of lethal PCa." (PMID 37435060, 2023). "In IBC, the higher numbers of CD1a+ and mature CD83+ DCs are associated with smaller tumor size, higher overall survival and a lower risk of relapse in triple-negative BC after neoadjuvant chemotherapy without pathological complete response." (PMID 37373062, 2023). "The mBc1 cluster expressed the pre-B cell receptor-associated molecule VPREB3, the B cell activation marker CD83, and genes associated with cell metabolism, cellular growth, and tumor progression (DDX54, PRDX6, GRHPR)." (PMID 36153593, 2022). "While previous reports suggest an abundance of immature dendritic cells in advanced CTCL lesions implicated in tumor progression, DC-1 highly expressed the maturation marker CD83." (PMID 33968070, 2021). "Tumor-associated CD83 + CCR7 + LAMP3+ DCs were found to selectively express in tumor tissue." (PMID 39256364, 2024). "CD83 is associated with mature DCs, which possess immune regulatory functions and can stimulate and inhibit the immune response against tumor antigens; hence, the immunosuppressive properties of mature DCs may facilitate the growth of MSGN." (PMID 37992142, 2024). "In addition, a statistically significant negative association was indicated between the expression of CD83 and the level of tumor purity." (PMID 38653742, 2024). "Similar to the increased antitumor CD8 T cell response observed in the expression data, these results show that tumor cell expression of CD83 is associated with the activation of CD8+ T cells and might promote their expansion." (PMID 39601621, 2024). "The total tumor weights for CD83-OV groups (n = 9) were significantly higher than that for the control (n = 8) and CD83-KD groups (n = 8), suggesting that the expression of CD83 was tightly linked to tumor burden." (PMID 32823589, 2020). "Moreover, different from peripheral blood pDCs, both lymph node and tumor-associated pDCs showed a discrete level of activation, assessed as surface CD83 expression." (PMID 21151495, 2010). "After the euthanasia of murine subjects, an assessment of oncolytic efficacy was performed through flow cytometry analysis of murine blood and tumor tissue, targeting CD83, CD86, CD8, and CD4." (PMID 39062070, 2024). "Studies have shown that CD83+ DCs (equivalent to DC-LAMP+ DCs) are distributed predominantly in the IM of the tumour stroma and are tightly attached to B-cell lymphoid follicles resembling GCs." (PMID 39136032, 2024). "Mature DCs (CD83+) are primarily located at the invasive tumor margins in iCCA, while a considerable number of immature DCs (CD1a+) are found inside the tumor." (PMID 39456636, 2024). "Our findings revealed that CD83+ tumor cells contribute to tumor growth suppression and are associated with enhanced cytotoxic T-cell profiles and activated CD8+ T cells." (PMID 39601621, 2024). "Given the key role of CD83 in modulating tumor–immune interactions, we sought to define which immune populations are impacted by CD83 expression in tumor cells." (PMID 39601621, 2024). "The flow cytometry analysis of the blood and tumor of mice with induced tumor treated with combined treatment revealed elevated levels of CD83, CD86, CD8, and CD4 (76.3, 66.9, 83.7, and 14.4%, respectively)." (PMID 39062070, 2024).
tumor (continued). "These collective studies suggest that the expression of CD83 by tumor cells confers a unique transcriptional signature, the effects of which are correlated with better survival outcomes in both human patients and mouse models of the disease." (PMID 39601621, 2024). "We found CD83 expression affected the level of Cd11b in human and mouse cells and increased CD83 enhanced tumor–immune communications." (PMID 39601621, 2024). "To determine how CD83 expression influences tumor features, we assessed age-matched P60 CD83OE, CD83KO, and control tumors." (PMID 39601621, 2024). "This study suggests the possibility that tumor–T cell–myeloid interactions are enhanced by tumoral expression of CD83." (PMID 39601621, 2024). "Increased proinflammatory cytokines were identified in CD83-overexpressing tumor conditions, which were also correlated with long-term CD8+ antitumor responses." (PMID 39601621, 2024). "In tumors with high CD83, we also saw an increased number of interactions and strength of the signal between CD83 tumor cells and CD45-positive cells." (PMID 39601621, 2024). "To identify the transcriptional features imparted onto tumor cells by the expression of CD83, we compared CD83+CD45– tumor cells from CD83OE tumor mice to CD83–CD45– tumor cells from control tumor mice using DEG analysis." (PMID 39601621, 2024). "Despite the varied outcomes and grades of our tumor samples, our analysis of CD83+ tumor cells revealed that a rare cell population is present in both IDHmut (7.7%) and IDHWT (3.78%) tumors." (PMID 39601621, 2024). "To determine if the effects of CD83 expression on tumor growth are reliant upon extrinsic cues, we derived cell lines from tumor-bearing mice and assessed proliferation in vitro with an EdU assay." (PMID 39601621, 2024). "CD83+ tumor cells promote signatures related to cytotoxic T cells, enhanced activation of CD8+ T cells, and increased proinflammatory cytokines." (PMID 39601621, 2024). "Bell observed a higher CD83 concentration in the peri-tumoral area and a higher CD1a concentration within the tumor tissues." (PMID 39529763, 2024). "Performing flow cytometry on seven additional samples from patients with HPSCC verified that LAMP3+ DCs were present in the tumor and expressed higher PD-L1, CD83, and CCL19 levels than LAMP3– DCs." (PMID 37853464, 2023). "CD83, a member of the immunoglobulin superfamily, is a novel marker to discriminate precursor exhausted T cells from terminally exhausted and bystander tumor-infiltrating T-lymphocytes." (PMID 36906640, 2023). "When monitored by the luciferase activity, both control and CD83-overexpressing CAR-T cells progressively accumulated at the tumor site and eventually controlled tumor growth in most of the treated mice." (PMID 36906640, 2023). "We investigated CD83 expression of tumor-infiltrating T cells in immunocompetent mouse tumor models." (PMID 36906640, 2023). "CD83-overexpressing CAR-T cells initially showed less efficient control of tumor growth, which is consistent with the in vitro data that ectopic expression of CD83 attenuated the production of cytolytic molecules." (PMID 36906640, 2023). "When analyzed on day 5 after T-cell injection, CD83 was more upregulated in the intratumoral CCR7+ CAR-T cell population than in CCR7− CAR-T cells in the tumor and T cells in the spleen." (PMID 36906640, 2023). "Compared with non-responders, patients with a partial response showed a significantly lower risk of relapse when their residual tumor exhibited high FOXP3, CD68, CD83, CD31 and CD34 content and IL15 expression but a low CD138 concentration." (PMID 37511057, 2023). "In contrast, co-culturing untreated tumor cells with the hmDCs even significantly decreased the expression of CD83 for the cell line HSC-4 and UM-Scc-47 as well as the activation marker CD86 for all cell lines, but the HPV-positive cell line UD-Scc-2." (PMID 37857049, 2023).